GAS5 (growth arrest specific 5)
Diseases named in the same sentence as GAS5 in open-access papers (continued):
Sharing a sentence is not in itself a finding about the gene and the disease.
melanoma (continued). "It was found that lncRNA GAS5 exhibited lower expression in melanoma tissues than that in the adjacent normal tissues (p < 0.05), which helped to distinguish patients with low expression of lncRNA GAS5 and that with lncRNA GAS5 high expression." (PMID 32308561, 2020). "Recent study has found that the long noncoding RNA, growth arrest-specific transcript 5 (GAS5) was downregulated in melanoma cells." (PMID 35006436, 2020). "GAS5 knockdown increases melanoma cell proliferation by inducing Cyclin D1, CDK4, and p27 expression and inhibiting apoptosis via increasing Bcl-2 expression." (PMID 31500396, 2019). "Melanoma samples from patients show significantly reduced GAS5 expression in advanced disease, such as larger tumor size and a high incidence of metastases." (PMID 31500396, 2019). "All but one (GAS5) of 13 lncRNAs reviewed are upregulated in melanoma compared with normal tissue, and three lncRNAs are suggested to be melanoma specific (RMEL3, SAMMSON, LLME23)." (PMID 28415644, 2017). "Overexpression of GAS5 in the SK-MEL-110 melanoma cell line reduced the migration and invasiveness and lead to a decrease in MMP2 expression, a protein specifically involved in type IV collagen degradation." (PMID 28415644, 2017). "Reduced expression of GAS5 was observed in the SK-MEL-110 melanoma cell line using RT-PCR compared to the other cell lines (HaCaT, A375, SK-MEL-28 and M21)." (PMID 28415644, 2017). "The results revealed that the downregulation of GAS5 expression in melanoma may be correlated with modification of methylation." (PMID 41463281, 2025). "A recent study investigated GAS5 methylation levels in melanoma to provide therapeutic targets." (PMID 41463281, 2025). "GAS5 interactions with miR-124(-3p) and miR-137(-3p) in OC have not been previously reported, although there is evidence of GAS5 involvement in the suppression of melanoma cell proliferation, migration, and invasion via the GAS5/miR-137 axis." (PMID 39519394, 2024). "GAS5 has been previously identified as tumor suppressor in melanoma." (PMID 37325482, 2023). "Similarly, Nuclear Factor-Kappa B Interacting lncRNA (NKILA) and growth-arrest specific 5 (GAS5) exert pro-apoptotic functions in melanoma by different mechanisms." (PMID 33503876, 2021). "Simultaneously, it was determined that GAS5 could inhibit cell proliferation, migration, and invasion of melanoma cells through miR-13730." (PMID 34625583, 2021). "In addition, lncRNA GAS5 has been proved to be down-regulated in melanoma tissues and inhibits growth, migration and invasion of melanoma cells." (PMID 35096622, 2021). "However, over-expression of GAS5 in melanoma cell lines induces a decreased expression of matrix metalloproteinases (MMPs), specifically involved in extracellular matrix (ECM) degradation." (PMID 33503876, 2021). "Knockdown of GAS5 by inducing G1/S cell cycle progression could increase melanoma cell proliferation." (PMID 33330110, 2020). "Moreover, knockdown of lncRNA growth arrest specific 5 (Gas5) in melanoma enhanced intracellular ROS via increased superoxide anion and NADPH oxidase 4 (NOX4)-oxidized GSH153." (PMID 32709863, 2020). "The correlation between lncRNA GAS5 expression and clinicopathological features in 75 cases of melanoma was analyzed, which suggested that the level of lncRNA GAS5 low expression in melanoma clinical specimens, was much higher than that of lncRNA GAS5 high expression (p < 0.05)." (PMID 32308561, 2020). "To test whether the lncRNA GAS5 was dysregulated in melanoma cells, we performed RT-qPCR assays for lncRNA GAS5 in 75 melanoma tissues and adjacent normal tissues from patients with melanoma." (PMID 32308561, 2020). "This study proposed a potential therapeutic target lncRNA growth arrest-specific transcript 5 (GAS5) for melanoma, due to its crucial role in oxidative stress and apoptosis of melanoma cells by regulating the enhancer of zeste homolog 2 (EZH2)-mediated CDKN1C expression." (PMID 32308561, 2020).
melanoma (continued). "Interestingly, GAS5 seems to repress melanoma tumorigenesis via miR-137, while MEG3 inhibits tumour growth and metastasis by modulating miR-21/E-cadherin axis." (PMID 33203119, 2020). "The lncRNA GAS5 expression pattern was examined in melanoma tissues and cells." (PMID 32308561, 2020). "Previous evidence has indicated the role of lncRNA GAS5 in the progression of melanoma, which could be the possible indicators for melanoma and could serve as a therapeutic target." (PMID 32308561, 2020). "Overexpression of lncRNA GAS5 or CDKN1C or EZH2 knockdown could inhibit cell viability but enhance melanoma cell apoptosis and oxidative stress." (PMID 32308561, 2020). "Hence, these findings suggest that lncRNA GAS5 acts as an inhibitor in melanoma pathogenesis and provides a potential therapeutic target for melanoma treatment." (PMID 32308561, 2020). "Consequently, our findings demonstrate that the elevation of lncRNA GAS5 upregulates CDKN1C to suppress the viability of melanoma cells and induce cell apoptosis as well as oxidative stress by inhibiting EZH2 expression and H3K27 trimethylation." (PMID 32308561, 2020). "GAS5 is the only reported lncRNA acting as tumor suppressor in melanoma." (PMID 28415644, 2017). "Therefore, it was indicated that overexpression of lncRNA GAS5 could block melanoma cell viability and stimulate the oxidative stress and apoptosis of melanoma cells." (PMID 32308561, 2020). "However, the research is still at the preclinical stage whilst the role and underlying mechanism of lncRNA GAS5 in melanoma are not comprehensively investigated." (PMID 32308561, 2020). "Importantly, lncRNA GAS5 was unraveled to act as a tumor suppressor in the progression of melanoma." (PMID 32308561, 2020). "Hence, these findings may provide a clue that lncRNA GAS5 was poorly expressed in melanoma and could be a possible candidate as tumor-inhibitor to affect the oxidative stress and apoptosis in melanoma cells." (PMID 32308561, 2020). "Thus here we may suggest, that in the future study, a larger cohort of clinical samples should be included in the research to further determine the underlying mechanism of lncRNA GAS5, EZH2, and CDKN1C in melanoma." (PMID 32308561, 2020). "The expression of EZH2 in melanoma cells is reported to be also regulated by other two different tumor suppressor lncRNAs, i.e., LINC-PINT and by GAS5, but using different strategies." (PMID 40282449, 2025). "Silencing lncRNA GAS5 accelerated the EZH2 expression as well as H3K27 trimethylation to suppress the CDKN1C transcription and oxidative stress in melanoma." (PMID 32308561, 2020). "The evidence provided by our study highlighted the involvement of lncRNA GAS5 in the translational suppression of EZH2 as well as the upregulation of CDKN1C, resulting in the promotion of melanoma cell apoptosis and oxidative stress." (PMID 32308561, 2020). "Collectively, our investigation displayed that the silencing of lncRNA GAS5 and CDKN1C or elevation of EZH2, accelerated the viability of melanoma cells while suppressed oxidative stress and apoptosis of melanoma cells." (PMID 32308561, 2020). "The correlation of lncRNA GAS5, EZH2, and CDKN1C with survival rate of melanoma patients was analyzed." (PMID 32308561, 2020). "High expression of EZH2 and poor expression of lncRNA GAS5 and CDKN1C was observed in melanoma tissues and found to be correlated with the reduction in survival expectancy of melanoma patients." (PMID 32308561, 2020). "Several studies have identified known lncRNAs that are abnormally expressed in melanoma, such as SAMMSON, HOTAIR, SLNCR1, BANCR, SPRY4-IT1, ANRIL, Llme23, UCA1, MALATA1, GAS5, H19, CASC15, PTENP1, and MIR31HG." (PMID 28225791, 2017). "In melanoma tissues and cells, the CpG islands in the promoter region of GAS5 are hypermethylated, while there is no methylation in normal tissues." (PMID 41463281, 2025).
melanoma (continued). "Conversely, GAS5 (Growth Arrest-Specific 5) is a lncRNA downregulated in melanoma tissue compared to adjacent noncancerous tissues." (PMID 40076754, 2025). "Thus, the present study assessed the functions of lncRNA GAS5, EZH2, and CDKN1C in the oxidative stress of melanoma cells." (PMID 32308561, 2020). "In subsequent experiments, we further identified that lncRNA GAS5 could upregulate CDKN1C to accelerate oxidative stress and apoptosis of melanoma cells and inhibit its viability by blocking EZH2 and H3K27 trimethylation." (PMID 32308561, 2020). "The reduced expression of lncRNA GAS5 contributed to redox balance and cell cycle progression through increasing expression of Cyclin D1, CDK4, and NOX4, suggesting downregulated GAS5 and increased ROS levels as promising diagnosis or prognosis biomarker for malignant melanoma." (PMID 35006436, 2020). "Moreover, GAS5 attenuates the expression and the activity of MMP2 and MMP9 and has a role in regulating the metastasis phenotype of melanoma cells; however, no data are published about the role of GAS5 as a regulator of MMP9 and MMP2 expression in IBD patients." (PMID 31652976, 2019).
osteosarcoma (27 papers, 2017 to 2025). A usually aggressive malignant bone-forming mesenchymal neoplasm, predominantly affecting adolescents and young adults. "However, we present here some very novel information for a role of miR-21 in GAS5-regulated lung metastases of osteosarcomas with underlying effect on the process of EMT." (PMID 34386496, 2021). "In HCC, oral cancer, and uterine cervical cancer, the promoter variant rs145204276 may impact GAS5’s tumor suppressive effect; nevertheless, its tumor suppressive activity has been described in osteosarcoma, where allele deletion was associated with enhanced GAS5 expression and smaller tumors." (PMID 35736636, 2022). "A recent study highlighted a significant repression of GAS5 in osteosarcoma patients, as well as a more prominent repression in patients with lung metastatic cancer." (PMID 39941145, 2025). "Upon further characterization in osteosarcoma cell lines, the GAS5 repression corresponded to upregulated epithelial–mesenchymal transition (EMT), a phenomenon which increases migration and invasion, both integral for metastasis." (PMID 39941145, 2025). "Long non‐coding RNA (LncRNA) GAS5 was observed to repress the osteosarcoma metastasis via sponging miR‐203a, which regulated PI3K‐AKT signaling in osteosarcoma." (PMID 39149855, 2024). "Taken together, GAS5 enhanced the sensitivity of osteosarcoma cells to DDP via GAS5/miR-26b-5p/TP53INP1 axis." (PMID 37993867, 2023). "The role and molecular mechanism of GAS5 in DDP-resistance of osteosarcoma were investigated in vivo and in vitro." (PMID 37993867, 2023). "The effects of GAS5 over-expression on proliferation and apoptosis of osteosarcoma DDP-resistant cell lines were analyzed." (PMID 37993867, 2023). "GAS5 was downregulated in osteosarcoma tissues compared with that in adjacent normal group, among which the levels of GAS5 were further suppressed in osteosarcoma tissues obtained from DDP-resistant patients." (PMID 37993867, 2023). "Meanwhile, expression level of GAS5 was dramatically suppressed in osteosarcoma cell lines in contrast with osteoblasts hFOB1.19, and was further suppressed in DDP-resistant osteosarcoma cells compared with DDP-sensitive ones." (PMID 37993867, 2023). "GAS5 was identified to be significantly lowly expressed in osteosarcoma samples especially in cisplatin-resistant (DDP-resistant) tissues." (PMID 37993867, 2023). "As report goes, GAS5 suppresses proliferation and invasion of osteosarcoma cells by sponging different microRNAs (miRNAs)." (PMID 37993867, 2023). "The combination of GAS5 and nanotechnology to improve the chemotherapy sensitivity of osteosarcoma is also a topic worth exploring in future research." (PMID 37993867, 2023). "Up-regulation of GAS5 contributed to the weakened malignancy in osteosarcoma cells and enhanced DDP chemoresistance by regulating miR-26b-5p/TP53INP1 axis." (PMID 37993867, 2023). "GAS5 expression in osteosarcoma tissues was used as the basis for clinicopathological analysis, and there was no statistical significance between clinical parameters and GAS5 expression." (PMID 37993867, 2023). "Further work has shown that GAS5 is involved in the occurrence and prognosis of bone diseases, such as osteoporosis, osteosarcoma, and postosteoporotic fracture." (PMID 35155450, 2021). "All the osteosarcoma cell lines had relatively downregulated GAS5 confirming the downregulation of GAS5 in our cell line models as well." (PMID 34386496, 2021). "GAS5 was generally downregulated in osteosarcoma patients (n = 24) compared to healthy controls (n = 10) and even more so in patients with lung metastatic disease(n = 11) compared to the patients without metastasis (n = 13)." (PMID 34386496, 2021). "We make this comment because not only GAS5 was downregulated in osteosarcomas in general, it was significantly further reduced in lung metastases." (PMID 34386496, 2021).
osteosarcoma (continued). "Our next goal was to work out the mechanism of action of GAS5 in osteosarcoma, and therefore, we turned to cell line models for detailed mechanistic studies." (PMID 34386496, 2021). "We first evaluated the levels of GAS5, by quantitative real-time PCR (qRT-PCR), in osteosarcoma patients (n = 24) and compared the levels of GAS5 in patients with those in the archived samples from healthy controls (n = 10)." (PMID 34386496, 2021). "Some of the tested miRNAs have previously been shown to be targeted by GAS5 in osteosarcoma, such as miR-221, miR-203a, miR-23a, and miR-663a." (PMID 34386496, 2021). "In this regard, the GAS5 expression level was significantly reduced (p < 0.001) in osteosarcoma tissues (n = 20) compared with normal tissues (n = 20), and was negatively correlated with miR-663a expression." (PMID 34771549, 2021). "Another interesting revelation from our analysis was that we observed a certain degree of specificity in terms of a role of GAS5 and miR-21 in lung metastasis of osteosarcomas." (PMID 34386496, 2021). "Our analysis revealed that both migration and invasion of osteosarcoma cells increased when GAS5 was downregulated." (PMID 34386496, 2021). "In this study, we report the status of growth arrest specific 5 (GAS5) in lung metastatic osteosarcomas." (PMID 34386496, 2021). "One lncRNA that has been investigated in a number of reports on osteosarcoma is the lncRNA growth arrest specific 5 (GAS5)." (PMID 34386496, 2021). "In our analysis for the role of GAS5 in osteosarcoma cells metastasis, we performed migration and invasion assays." (PMID 34386496, 2021). "The downregulation of GAS5 was even more significant in the osteosarcoma patients with lung metastasis (p < 0.001 vs. controls and p < 0.01 vs. osteosarcoma patients with no metastasis)." (PMID 34386496, 2021). "Our observations reveal a possible role of GAS5 and miR-21 in lung metastasis of osteosarcoma, presenting them as novel targets for therapy." (PMID 34386496, 2021). "In our study, we determined a role of miR-21 in EMT of osteosarcoma, particularly in the context of regulation by lncRNA GAS5." (PMID 34386496, 2021). "Our analysis of GAS5 levels in different osteosarcoma cell lines revealed that in hFOB 1.19, the normal control cells had the highest expression of GAS5." (PMID 34386496, 2021). "miR-21, as presented above, is involved in GAS5 effects on osteosarcoma cells, and its upregulation can reverse the effects of GAS5 silencing." (PMID 34386496, 2021). "It seems reasonable because increased GAS5 expression has been reported to inhibit cell growth of osteosarcoma through the mIR-221/aplasia Ras homologue member I pathway." (PMID 32547314, 2020). "Down-regulation of lncRNA GAS5 (growth arrest specific 5) represses osteosarcoma cells growth and metastasis in osteosarcoma." (PMID 31142627, 2019). "The other study showed that lncRNA GAS5 was down-regulated in osteosarcoma and its overexpression suppressed tumor growth of osteosarcoma." (PMID 29245999, 2017). "Notably, the proliferation of osteosarcoma cells decreased following the activation of the GAS5/miR-23a axis via the PTEN/PI3K/AKT pathway." (PMID 39941145, 2025). "Extensive studies have shown that GAS5 plays an important role in various diseases, such as diabetic wound healing, asthma, pneumonia, and several types of cancers, mainly including cholangiocarcinoma, laryngeal squamous cell carcinoma, and osteosarcoma." (PMID 38407972, 2024). "Briefly, GAS5 expression levels in osteosarcoma tissues and cell lines were detected." (PMID 37993867, 2023). "Over-expressed GAS5 prominently increased the sensitivity of osteosarcoma cells to DDP in vitro." (PMID 37993867, 2023). "GAS5 was down-regulated and functioned as a cancer suppressor gene in osteosarcoma." (PMID 37993867, 2023). "The effect of GAS5 expression level in different stages of osteosarcoma can be elaborated." (PMID 37993867, 2023).